BECN1 (beclin 1)
Diseases named in the same sentence as BECN1 in open-access papers (continued):
Sharing a sentence is not in itself a finding about the gene and the disease.
tumor (continued). "Autophagic regulator AMBRA1 (regulator 1 of BECN1 and autophagy) can influence tumor metabolism by regulating c-Myc degradation." (PMID 33763351, 2021). "Our results, unlike the data in the literature, show that the increase in Beclin-1 expression is correlated with the degree of tumour infiltration (expressed in mm)." (PMID 34769649, 2021). "The scoring intensity was further classified into tissues with negative staining and positive staining, which showed that positive scores of Beclin-1 and Parkin were significantly high in tumor tissues compared to other markers." (PMID 34490076, 2021). "We further detected high Beclin 1 expression, low p62 accumulation (representing high autophagy activation), and increased FoxO1 staining in the tumors as well as in the nucleus of tumor tissues in amiodarone treatment group." (PMID 34737955, 2021). "The acidity of the tumor environment induces the drug release and therefore a tumor-targeted action of various anti-cancer molecules such as chemotherapeutics or apoptosis/autophagy inducers (Beclin 1)." (PMID 33806772, 2021). "All examined adjacent non tumor liver tissue revealed low expression of Beclin-1 (IRS <6) corresponded to the normal expression pattern." (PMID 33906303, 2021). "In further analysis, we established cells with different Beclin-1 and Bcl-2 expression states using plasmid vectors and siRNA before making in vitro observations of the invasiveness of tumor cells." (PMID 34257544, 2021). "Some studies have also found that drug-induced tumor cell death is related to the Bcl-2–Beclin 1 complex pathway." (PMID 34830185, 2021). "As a tumor suppressor gene, Beclin-1 is a crucial modifier of autophagy and is involved in the activation of autophagy and the formation of autophagosomes." (PMID 34093717, 2021). "Recently, the primary role of BECN1 in tumor suppression as a positive regulator of autophagy was partially hidden by the discovery of alternative pathways in which it plays regulatory roles." (PMID 34830777, 2021). "Immunohistochemistry revealed that LC3, Beclin-1, and p62 expression levels were elevated in 82.5% (33 of 40), 62.5% (25 of 40), and 76.5% (27 of 40) of tumor specimens, respectively." (PMID 34273969, 2021). "In line with our observations, autophagy inhibition by Becn1 knockdown, which blocks autophagosome production, significantly induces a tumor-suppressive immune microenvironment." (PMID 33809137, 2021). "Beclin 1, a mammalian homologue of yeast Atg6/Vps30, initiates autophagy pathway acting also as tumor suppressor." (PMID 33212974, 2020). "Tumor susceptibility to the cytotoxic effect and tumor cell lysis of T lymphocytes are restored through hydroxychloroquine (HCQ)-mediated autophagy inhibition or knockdown of ATG and Beclin-1 genes." (PMID 33194736, 2020). "Collectively, these results indicate that Beclin 1 down-regulation renders the AML cells sensitive to necroptotic cell death, implying that Beclin 1 can be used as a plausible therapeutic target for necroptosis-induced anti-tumour therapy." (PMID 32457484, 2020). "In accordance with a tumor suppressor role, a decreased expression of Beclin-1 at mRNA and protein levels have been found in human brain tumor samples, compared to non-tumoral lesions." (PMID 32245178, 2020). "The concordance of BRCA1 deletions and BECN1 deletions between tumor types is expected from their close proximity on chromosome 17." (PMID 31923184, 2020). "Among the Atg genes, beclin 1 (Atg6) is an essential tumor suppressor that modulates the initiation and regulation of autophagy." (PMID 32765806, 2020). "IHC staining showed that the expression of BECN1 was markedly decreased in tumor tissues compared with the adjacent normal samples." (PMID 32358527, 2020). "The evidence that Beclin-1 expression is monoallelicaly suppressed in some human breast, ovarian and prostatic cancer cell lines, suggests that it acts as a tumor suppressor gene." (PMID 33330070, 2020).
tumor (continued). "It has been proposed that a drop in the expression of Beclin-1 in GBM tissue enhances EGFR overexpression; therefore, higher EGFR levels and decreased levels of the protein Beclin-1 have been associated with tumor progression and a poorer prognosis." (PMID 32707662, 2020). "Later on, it was discovered that HER2 binds to Beclin 1 in HER2+ tumor cells and inhibits autophagy." (PMID 33287140, 2020). "Blocking the expression of PD-L2 in osteosarcoma inhibits LC3-II and Beclin-1, impeding the ability of tumor cells to invade surrounding tissue." (PMID 33117715, 2020). "Endophilin B1 (Bif-1), another recognized tumor suppressor, integrates with Beclin-1 via UVRAG to improve Class III PI 3-kinase complex activity, and further loss of Bif-1 suppresses autophagosome development." (PMID 32121322, 2020). "The first important experimental data sustaining the possible tumor suppressor role of autophagy were obtained in studies targeting Beclin-1." (PMID 33297472, 2020). "Beclin-1, a regulator of autophagy initiation, was the first tumor suppressor gene to be found in autophagy-related proteins in human cancers." (PMID 32466337, 2020). "Serendipitously, Becn1 has only been studied for haploinsufficient tumor suppressor roles in vivo due to the early embryonic lethality of homozygous deletion." (PMID 31923184, 2020). "Protein expression of ULK1 and Beclin-1, and the ratio of LC 3 II/I were significantly reduced in the tumor tissue of BJE-H group." (PMID 32411003, 2020). "Impairment of autophagy with BECN1 ablation is also beneficial to increase NK infiltration and inhibit tumor growth in a melanoma tumor model." (PMID 33324568, 2020). "Western Blot results showed that the protein expression of LC3-II and Beclin-1 in the tumor tissue increased significantly, and the protein expression of p62 decreased significantly." (PMID 33194612, 2020). "In contrast, CDK inhibitors stimulate autophagy by releasing BECN1, which results in the promotion of tumor growth." (PMID 32802407, 2020). "In melanoma, targeting of autophagy gene BECN1 increased the infiltration of functional NK cells into tumours." (PMID 32745353, 2020). "BECN1 represents an essential modulator of phagophore nucleation and, also, an important player in tumor suppression molecular mechanism." (PMID 33297472, 2020). "The role of Beclin 1 as an anti-necroptotic factor prompted us to further explore the effect of Beclin 1 depletion, as an anti-tumour therapy." (PMID 32457484, 2020). "These experimental observations outlined the Beclin-1 role as a haplo-insufficient tumor suppressor involved in the molecular mechanisms of several human cancers." (PMID 33297472, 2020). "After SNHG1 expression was silenced and EZH2 was overexpressed, the protein expression of LC3-II and Beclin-1 in the tumor tissue was significantly reduced while the protein expression of p62 was significantly increased." (PMID 33194612, 2020). "Beclin-1 which is a homolog of yeast Atg6/Vps30 autophagy related gene, is also involved in autophagy and tumor genesis as well as is an essential factor for autophagosome formation." (PMID 32426183, 2020). "BECN1 is a critical regulator of autophagy, which plays important roles in tumor formation and metastasis." (PMID 32358527, 2020). "The autophagy protein Beclin-1 serves as a tumor suppressor or tumor promoter in a context-dependent manner." (PMID 32649310, 2020). "Beclin 1 is an important factor in the regulation of autophagy and is considered as a tumor inhibitor." (PMID 32733943, 2020). "The beclin-1 protein is a tumor suppressor and a central regulator of autophagy critical to the nucleation phase of autophagy." (PMID 32487196, 2020). "MiRNA-30a, a miRNA that targets beclin 1, was significantly reduced in tumor cells treated with CDDP." (PMID 30744689, 2019).
tumor (continued). "Specifically, inhibitors of the PI3K/Akt/mTOR pathway or overexpression of autophagy-inducing gene products such as PTEN and Beclin-1 are potentially feasible to treat tumor through autophagy pathway." (PMID 31429768, 2019). "BECN1 as a tumor suppressor is also evidenced by the identification of their binding partners, most of which are implicated in tumorigenesis, such as BCL-2." (PMID 30696802, 2019). "Decreasing levels of Beclin-1 leads tumor cells to overexpress CCL5 cytokine, which regulates the trafficking of NK cells to the tumors." (PMID 31013961, 2019). "Further studies demonstrated that BRCA1 loss is the driver mutation in hereditary and sporadic breast cancer, casting doubt on BECN1′s role as a tumor suppressor." (PMID 31027346, 2019). "Beclin 1 is a mammalian autophagy protein involved in diverse biological processes, including tumor suppression and cell death." (PMID 31172425, 2019). "A total of 97 (85.9%) and 77 (68.2%) tumor tissues exhibited positive immunohistochemical staining for Beclin-1 and ARID1A, respectively; 96 (85.0%) and 105 (92.9%) samples stained positive for CA9 and IDH1, respectively." (PMID 30849962, 2019). "In NSCLC, previous studies demonstrated that the expression of BECN1 was significantly reduced in tumor tissues." (PMID 31272261, 2019). "The connection between BECN1 and cancer was first discovered in 1999, and now BECN1 is commonly known as a haploid-insufficient tumor suppressor." (PMID 31272261, 2019). "The combination of 17-AAG (Hsp90 inhibitor) with Flavopiridol enhanced tumour cell apoptosis through BECN-1 degradation, ERK inactivation and autophagy suppression." (PMID 30704144, 2019). "Forced expression of miRNA-30a significantly reduced beclin 1 and the autophagic activity of tumor cells induced by CDDP." (PMID 30744689, 2019). "Our results show that alterations of Beclin-1 have a tendency for muscle-invasive bladder cancer and tumor stages." (PMID 31772653, 2019). "The Beclin 1 phospho-mimetic mutant (Beclin 1 Y229/233/352E; Beclin 1 EEE) leads to autophagy suppression and a faster tumor growth in xenograft models as compared to the Beclin 1 wild-type control." (PMID 31877888, 2019). "As far as other autophagy-related proteins are concerned, Beclin 1-a Bcl-2 interacting protein - is the first identified mammalian gene to mediate autophagy, also having tumour suppressor and antiviral function." (PMID 31065032, 2019). "In vivo tumour xenograft assays also demonstrate the anti‐tumour effect of BECN1 by inducing ferroptosis." (PMID 31232522, 2019). "Introduction of BECN1 to the lungs of K-ras (LA1) mice reduced the numbers of tumor on the surface and histopathological tumor progression in the lungs of K-ras (LA1) mice." (PMID 31272261, 2019). "Beclin 1, the mammalian ortholog of yeast Atg6/Vps30, is an essential autophagy protein and has been shown to play a role in tumor suppression." (PMID 31877888, 2019). "The LC3-II and beclin-1 expressions were accumulated by anlotinib and CQ, indicating elevated levels of autophagy in tumor tissues." (PMID 30755242, 2019). "Beclin 1 has also attracted attention as a haploinsufficient tumor suppressor gene, as it was found to be monoallelically deleted in several cancers." (PMID 30397185, 2019). "AMBRA1-deficiency leads to uncontrolled cell proliferation as well, and AMBRA1 can also interact with BECN1, again supporting a tumor-suppressive function of autophagy." (PMID 31671879, 2019). "BECN1 (Beclin 1) is a central regulator of autophagy and a haplo-insufficient tumor suppressor that is decreased in many human tumors." (PMID 30696802, 2019). "Several studies support that inhibition of Beclin-1 reduces tumor growth and enhances anti-tumor NK cell activity." (PMID 31013961, 2019).
tumor (continued). "In contrast, increased stimulation of autophagy provided by Beclin 1 overexpression can block tumor development." (PMID 29783720, 2018). "Together, these data suggested that EI24 suppresses tumor proliferation possibly by the activation of autophagy to regulate the Beclin-1/p62/c-Myc signaling pathway." (PMID 30369947, 2018). "Beclin-1 acts as a tumor suppressor gene to regulate and promote autophagy by enhancing PI3KC3 kinase activity, thereby inhibiting tumor growth." (PMID 29549251, 2018). "Akt mediated phosphorylation at S234 and S295 leads to the suppression of BECN1 functions in autophagy and tumor suppression." (PMID 30370269, 2018). "Genetic inactivation of Beclin-1, an autophagy regulator, significantly reverses mitochondrial abnormalities and tumor development in ATM-null mice, independently of DDR." (PMID 29616191, 2018). "Initially, it was considered a mechanism for tumor-suppression, since disruption of genes related to autophagy, such as beclin-1, resulted in tumor development." (PMID 29581864, 2018). "Mutations in BECN1 are often present in various types of tumors, so it is believed that Beclin-1 is a tumor suppressor." (PMID 30344951, 2018). "Beclin-1 (also called autophagy-related gene 6 or Atg6) positive staining was found in 46 out of 123 (37.4%) tumor samples." (PMID 29545906, 2018). "Beclin 1 is important in the formation of the phagophore, suggesting that Beclin 1 functions as a tumor suppressor." (PMID 30400561, 2018). "A previous study found that Beclin-1 accelerates the degradation of c-Myc and that the Beclin-1/p62/c-Myc signaling pathway functions in regulating tumor proliferation." (PMID 30369947, 2018). "We further examined the expression of E-cadherin, proliferating cell nuclear antigen (PCNA) and Beclin-1 in the xenograft tumor tissue specimens." (PMID 28176874, 2017). "For example, activation of pro-autophagic Beclin-1 expression by Beclin-1-armed oncolytic adenoviruses enhances the autophagic death of malignant tumor cells." (PMID 28698504, 2017). "Compared with the CAOV3 group, significantly higher expression of Lewis y antigen, higher levels of ubiquitination, LC3 and Beclin 1, but significantly lower expression of p27 and p62 in tumor tissues were observed in the CAOV3-FUT1 group." (PMID 29299130, 2017). "Supporting the role of autophagy as a tumor suppressor, the monoallelic deletion of the Beclin 1 gene, the mammalian orthologue of yeast Atg6 involved in autophagosome biogenesis, is detected in 40–75% of human sporadic cancers." (PMID 29112132, 2017). "Beclin-1 is known as haplo-insufficient tumor-suppressor and accumulating evidence of data suggests its down-regulation in cancers." (PMID 28428777, 2017). "Remarkably, LY3023414's anti-tumor activity was further augmented against the Beclin-1-silenced U251MG tumors." (PMID 29228741, 2017). "For example, the deletion of Beclin 1, ATG5, or ATG7 were found to associate with the tumor phenotype of HCC." (PMID 28915706, 2017). "Consistently, one clinical study showed that Beclin-1 acted as a tumor suppressor in the development or progression of TSCC." (PMID 28526807, 2017). "In CRC cells, Beclin 1-dependent autophagy appears to be required for the maintenance of tumor cell survival, as knocking down of Beclin 1 sensitizes cells to icaritin-induced apoptosis." (PMID 28977986, 2017). "Immunoreactivity for LC3b and Beclin 1 was low in benign prostatic tissue (BPH, 2.5% and 24.4%, p<0.001)." (PMID 28423666, 2017). "Estimated tumor volume, daily tumor growth and the tumor weight were most significantly inhibited in TW-37-treated Beclin-1-silenced tumor group (“shBec-1+TW-37”)." (PMID 29065135, 2017). "Remarkably, LY3023414's anti-tumor activity in vivo was further augmented against Beclin-1-sh-expressing tumors." (PMID 29228741, 2017).
tumor (continued). "Beclin 1, which regulates the initiation stages of autophagosome formation, plays a role as a tumor suppressor." (PMID 29209152, 2017). "This appears to be due to a direct anti-survival effect of autophagy in tumor cells since autophagy inhibition by Beclin-1 siRNA enhances tumor cell growth and suppresses tumor cell death in vitro." (PMID 29113343, 2017). "Previously, it is known that this phosphorylation site is essential for the tumor suppressor function of BECN1." (PMID 28085066, 2017). "And western blot analysis illustrated that cleavage of Caspase-3, PARP, Caspase-8, and Caspase-9 were significantly induced by ACT, and LC3B-I/II and Beclin 1 were also potentiated due to ACT treatment in tumor samples." (PMID 29348843, 2017). "The expression of autophagy proteins (LC3, Beclin-1, and p62) in adjacent non-tumor tissues was scored by immunohistochemical staining." (PMID 29190884, 2017). "Vps34, a member of the phosphatidylinositol 3-/4 (PI3/PI4)-kinase family, plays an important role in the regulation of mTOR protein synthesis, and also forms a complex with beclin-1 that promotes autophagy and tumor suppression." (PMID 27070592, 2016). "The activation of the process can be oncogenic by contributing to tumor cell survival, besides the data from autophagy defective Beclin-1 knockout mice also suggest a tumor suppressive activity." (PMID 27462784, 2016). "BECN1 is a haploinsufficient tumor suppressor, yet once a tumor forms and expands, tumors require autophagy for essential metabolites, especially in hypoxic or otherwise nutrient-poor tumors." (PMID 27391266, 2016). "On another account, autophagy displays a tumour suppressive role as has been suggested for Beclin-1 or ATG4C." (PMID 27256984, 2016). "Beclin 1 has many cell functions, such as inducing autophagosome formation and acting as a tumor suppressor." (PMID 27846885, 2016). "RNF216 promoted CRC cell proliferation and migration in vitro and in vivo, largely by enhancing proteasomal degradation of BECN1, a key autophagy regulator and tumor suppressor." (PMID 27203674, 2016). "BECN1, an autophagy initiation gene also involved in ploidy homeostasis, increases tumor formation when monoallelically deleted." (PMID 27391266, 2016). "Remarkably, Beclin-1 showed a completely reciprocal expression pattern compared with EHMT2 in tumor tissue." (PMID 27174920, 2016). "Meanwhile, in the nude mouse transplantation model, CD147 and Beclin 1 protein was also increased in tumor cells transfected with FUT1 as compared to untransfected cells." (PMID 27863372, 2016). "A few earlier studies reported an important role of the miR-30 family in sensitizing tumor cells to the conventional therapeutic agents via suppression of Beclin-1 mediated autophagy." (PMID 27388765, 2016). "Our results confirmed the inhibitory role of autophagy in CRC development, consistent with other reports of BECN1-mediated tumor progression inhibition." (PMID 27203674, 2016). "Using immunohistochemical analysis, the distribution of Beclin 1 is mainly found in cytoplasm of tumor cells." (PMID 26910278, 2016). "Beclin 1 has emerged as a haploinsufficient tumor suppression gene in a variety of human carcinomas." (PMID 27683118, 2016). "The role played by Beclin 1 and Ambra1 as tumour suppressors is also evidenced by the identification of their binding partners, most of which are implicated in tumorigenesis, such as Bcl-2." (PMID 26735341, 2016). "In our study, high Beclin-1 expression was significantly correlated with tumor size (p = 0.001), histological grade (p < 0.001), LN metastasis (p < 0.001), TNM stage (p < 0.001), VCE (p = 0.013), and high SIRT1 expression (p < 0.001)." (PMID 28070138, 2016). "p62 and Beclin-1 immunohistochemistry demonstrated diffuse cytoplasmic staining and occasionally dot-like staining in the tumour specimens." (PMID 27444698, 2016).